KLRG1 (killer cell lectin like receptor G1)
Diseases named in the same sentence as KLRG1 in open-access papers (continued):
Sharing a sentence is not in itself a finding about the gene and the disease.
leukemia (2 papers, 2025). A malignant (clonal) hematologic disorder, involving hematopoietic stem cells and characterized by the presence of primitive or atypical myeloid or lymphoid cells in the bone marrow and the blood. "To dynamically monitor ST2+ Treg cells in malignant BM niches, we developed two aggressive leukemic models: MLL-AF9eGFP and DNMT3A/FLT3ITD, and confirmed in both the increases of KLRG1+ST2+ Treg cells in the BM TME with the progression of leukemia." (PMID 40691440, 2025). "We have also shown that in leukemia, as shown for other diseases, a large percentage of tissue-resident ST2+ Treg cells express KLRG1 and that frequencies of KLRG1+ST2+ Treg cells are correlated with total ST2+ Treg cells, although slightly smaller than total ST2+ Treg cells." (PMID 40691440, 2025). "We observed that BM ST2+ Treg cell, KLRG1+ST2+ Treg cell percentages and numbers rose over time after leukemia challenge as compared to the no tumor condition in both models." (PMID 40691440, 2025).
multiple myeloma (2 papers, 2021). "While exposure to repetitive stimulations with BCMA-expressing human KMS-11 multiple myeloma cells led to the expression of inhibitory receptors such as PD-1 and KLRG1, p16INK4a knockdown increased the fraction of Ki67+ cells and restricted the development of SA-β-Gal-expressing CAR T cells." (PMID 34434190, 2021).
pancreatic cancer (2 papers, 2020 to 2023). "In the absence of Cxcr3, splenic Klrg1 + GzmB + antitumor T cells wain while pancreatic cancer disseminates suggesting a role for these cells in eliminating circulating metastatic tumor cells." (PMID 36472588, 2023).
pemphigus foliaceus (2 papers, 2020 to 2023). Pemphigus foliaceous is a rare superficial pemphigus disease characterized by multiple, pruritic, scaly, crusted cutaneous erosions, with flaky circumscribed patches, localized mostly on the face, scalp, trunk and extremities, often presenting an erythematous base. "As regards active or severe lesions in the course of pemphigus foliaceus, the miRNA concentration of KLRG1 was significantly higher." (PMID 37298095, 2023). "Additionally, the role of interactions between E-cadherin/KLRG1/miR-584-5p and E-cadherin itself in the development of vesicular lesions is emphasized by the fact that 100% of patients with pemphigus foliaceus were found to have anti-E-cadherin antibodies." (PMID 37298095, 2023).
rheumatoid arthritis (2 papers, 2024). A chronic, systemic autoimmune disorder characterized by inflammation in the synovial membranes and articular surfaces. "A study of rheumatoid arthritis single-cell RNA sequencing data demonstrated that five genes, KLRG1, CRTAM, SLAMF7, PTPN2, and KLRD1, were downregulated in activated and effector T cells isolated from synovial fluids." (PMID 38254179, 2024).
systemic sclerosis (2 papers, 2022 to 2023). A chronic disorder, possibly autoimmune, marked by excessive production of collagen which results in hardening and thickening of body tissues. "Alongside TL1A, experiments adding TGF-β to ILC2 isolated from peripheral blood of subjects with systemic sclerosis that were cultured on dermal fibroblast showed decreased IL-10 production and dramatically decreased KLRG1 expression on ILC2, associated with IL-10 generation." (PMID 37947634, 2023). "In systemic sclerosis, skin biopsies show increased overall ILC2 numbers compared to healthy donors, and KLRG1-ILC2 specifically were elevated compared to KLRG1+ILC2." (PMID 37947634, 2023). "In human ILC210s from patients with systemic sclerosis (SSc), treatment with TGF-β dramatically decreased the production of IL-10 and reduced KLRG1 expression, an ILC2 surface marker found to be required for IL-10 production." (PMID 36275689, 2022).
ulcerative colitis (2 papers, 2021 to 2022). An inflammatory bowel disease involving the mucosal surface of the large intestine and rectum. "In line with our study, single cell RNA-sequencing of colonic T cells showed presence of multiple CD8+ Trm cell clusters, of which a KLRG1+EOMES+ITGB2+ subset is enriched in ulcerative colitis, and the CD103+ population in healthy control subjects." (PMID 34224909, 2021).
ZIKV infection (2 papers, 2017 to 2025). "In addition, KLRG1+ CD8+ effector T cells and effector memory T cells as well as CD8+ T cells expressing granzyme B, interleukin 2 (IL-2) and IFN-γ were more frequently detected in B6 mice following ZIKV infection, indicating the activation of CD8+ T cell response in vivo." (PMID 40920828, 2025).
acute myeloid leukemia (1 paper, 2024). Acute myeloid leukemia (AML) is a group of neoplasms arising from precursor cells committed to the myeloid cell-line differentiation. "KLRG1 expression is increased on a variety of immune cells in patients with a variety of HMs, including chronic lymphocytic leukemia (CLL), follicular lymphoma (FL), acute myeloid leukemia (AML), and multiple myeloma (MM)." (PMID 38898461, 2024).
adenovirus infection (1 paper, 2016). "A similar but less profound induction of KLRG1+ SLEC was also noticed in mice during the early phase of an adenovirus infection plus anti-OX40 co-stimulation by a recent publication." (PMID 27874054, 2016).
airway hyperresponsiveness (1 paper, 2019). "In case of lung inflammation such as papain-induced airway hyperresponsiveness, the trafficking of leukocytes is important to recruit inflammatory subsets and we demonstrated that CXCR6 deficiency was preventing the recruitment of new incoming mature activated KLRG1+ NK cells or iILC2." (PMID 31690060, 2019).
allergic asthma (1 paper, 2021). A asthma with a basis in a pathological type I hypersensitivity reaction. "Very recently, IL-10-producing KLRG1+ ILC2s emerged as other hypothetically interesting candidates for therapeutic cell transfer in the context of allergic asthma therapy." (PMID 34177944, 2021).
Alzheimer disease (1 paper, 2013). A progressive, neurodegenerative disease characterized by loss of function and death of nerve cells in several areas of the brain leading to loss of cognitive function such as memory and language. "For example, the increased expression of KLRG1, which belongs to the killer cell lectin-like receptor family, is commonly considered a senescence marker in patients with Alzheimer’s disease." (PMID 23936146, 2013).
amyloid (1 paper, 2024). "By using a GLM with sex and age as covariates on T cell subsets, we found that CD8+ effector T cells and CD57+ KLRG1+ CD4+ terminally differentiated effector memory T cells were higher in MCI patients with amyloid pathology." (PMID 38658964, 2024).
Arthritis (1 paper, 2022). Inflammation of a joint. "Notably, non-classical CD4+CD49b+KLRG1+ Tregs have been shown to dampen arthritis severity in an IL-10-dependent but Foxp3-independent manner." (PMID 35572605, 2022). "Another group reported the absence of KLRG1 upregulation in effector Tregs in arthritis patients." (PMID 35572605, 2022).
atherosclerosis (1 paper, 2019). A disease characterized by the build-up of fatty material and calcium deposition in the arterial wall resulting in partial or complete occlusion of the arterial lumen. "Expansion of type 2 innate lymphoid cells (ILC2s) in hypercholesterolaemic mice protects against atherosclerosis while different ILC2 subsets have been described (natural, inflammatory) based on their suppression of tumorigenicity 2 (ST2) and killer-cell lectin like receptor G1 (KLRG1) expression." (PMID 31823769, 2019).
atrial fibrillation (1 paper, 2025). A disorder characterized by an electrocardiographic finding of a supraventricular arrhythmia characterized by the replacement of consistent P waves by rapid oscillations or fibrillatory waves that vary in size, shape and timing and are accompanied by an irregular ventricular response. "For example, senescent CD8+ T cells, labeled with CD57+KLRG1+ CD27−CD28−, are enriched in both peripheral circulation and atrial myocardium of patients with atrial fibrillation (AF), promoting AF onset and postablation recurrence by disrupting intracellular calcium homeostasis." (PMID 41427020, 2025).
B cell lymphoma (1 paper, 2018). "Effective immunotherapy in mice with B cell lymphoma enhances expansion of KLRG1 expressing T lymphocytes." (PMID 29587679, 2018).
bladder cancer (1 paper, 2025). "As KLRG1 downregulation accompanied increased proliferation in the steady state in standard-of-care patients with bladder cancer, we looked at how PD-1 blockade affected coregulation of KLRG1 and proliferative capacity in clonally related cells." (PMID 40299576, 2025). "In both untreated and immunotherapy-treated patients with bladder cancer, proliferation of circulating cytotoxic CD4+ T cells was accompanied by downregulation of KLRG1." (PMID 40299576, 2025). "Cytotoxic CD4+ circulate between the blood and tumor of bladder cancer patients, where they exist as clonally related but distinct pools of granzyme B+ effector cells dually inhibited by PD-1 and KLRG1, and effector memory granzyme K+ cells that are not mobilized by PD-1 blockade." (PMID 40299576, 2025).
cervical cancer (1 paper, 2019). A primary or metastatic malignant neoplasm involving the cervix. "Furthermore, we found that a higher frequency of advanced differentiation stage T cells (CD27–CCR7–CD45RA–) among the “shared” subset (PD-1+Tim-3+TIGIT+2B4+KLRG-1–CTLA-4–) in bulk CD8 TILs was associated with poorly differentiated cancer type in cervical cancer patients." (PMID 31709176, 2019). "We further conducted T-cell differentiation analysis of the identified shared subset, PD-1+TIGIT+2B4+Tim-3+KLRG-1–CTLA-4– in bulk CD8 TILs from 10 cervical cancer patients." (PMID 31709176, 2019). "Conversely, the majority (60%) of PD-1+TIGIT+2B4+Tim-3+KLRG-1–CTLA-4– CD8 TILs from most (4/5) of the moderately differentiated cervical cancer samples displayed an intermediate T-cell differentiation phenotype, and a minor fraction (40%) displayed advanced T-cell differentiation phenotypes." (PMID 31709176, 2019).
chronic hepatitis (1 paper, 2024). An active inflammatory process affecting the liver for more than six months. "However, only the chronic infection (ALT < 40 U/L) and chronic hepatitis (ALT > 40 U/L) groups were found to exhibit this reduction in KLRG1 expression compared to the HCs." (PMID 38776335, 2024).
chronic hepatitis C (1 paper, 2022). "Additionally, it was found that the expression of KLRG1 increased in chronic hepatitis C." (PMID 35413989, 2022).
colorectal tumors (1 paper, 2021). "While KLRG1’s expression on ILC in the context of cancer is relatively unexplored, KLRG1-expressing ILC2 are found within the circulation of healthy donors, and the non-tumoral tissues, lung and colorectal tumors of cancer patients." (PMID 34885076, 2021).
depression (1 paper, 2024). "This study conducted a comprehensive bioinformatics analysis, identifying six core genes (BCL7A, GPR18, GRB10, KLRG1, TDRD9, and THEM4) associated with depression and validating their diagnostic value in the context of the disorder." (PMID 39867577, 2024). "The results indicated that BCL7A (AUC: 0.656), GPR18 (AUC: 0.9677), GRB10 (AUC: 0.678), KLRG1 (AUC: 0.661), TDRD9 (AUC: 0.698), and THEM4 (AUC: 0.678) exhibit high diagnostic value for depression." (PMID 39867577, 2024). "We identified six core genes (GRB10, TDRD9, BCL7A, GPR18, KLRG1, and THEM4) significantly associated with depression and cancer." (PMID 39867577, 2024). "In depression, GRB10 and TDRD9, involved in cell growth and stress responses, exhibited elevated expression, while BCL7A, GPR18, KLRG1, and THEM4, linked to immune regulation and apoptosis, showed reduced expression, suggesting dysregulated cellular signaling and impaired immune function." (PMID 39867577, 2024). "qPCR results demonstrated that, compared to the normal control group, the expression of GRB10 and TDRD9 was significantly elevated in the blood of depression patients, while the expression of BCL7A, GPR18, KLRG1, and THEM4 was significantly reduced." (PMID 39867577, 2024). "These pathways suggest that BCL7A, GPR18, KLRG1, and THEM4 play roles in immune signaling and metabolic pathways, further underscoring their relevance to depression." (PMID 39867577, 2024). "To more accurately predict and assess the progression of depression, we constructed a nomogram model for depression diagnosis based on the core genes (GRB10, TDRD9, BCL7A, GPR18, KLRG1, and THEM4) using the rms package." (PMID 39867577, 2024). "Among them, GRB10 and TDRD9 were significantly upregulated, while BCL7A, GPR18, KLRG1, and THEM4 were significantly downregulated in patients with depression." (PMID 39867577, 2024). "To investigate the correlation between cancer and depression, we examined the expression of BCL7A, GPR18, GRB10, KLRG1, TDRD9, and THEM4 across various cancer types using the TCGA database." (PMID 39867577, 2024). "We identified six core genes (BCL7A, GPR18, GRB10, KLRG1, TDRD9, and THEM4), confirming their critical value in diagnosing depression." (PMID 39867577, 2024). "Similarly, BCL7A, GPR18, KLRG1, and THEM4, which are downregulated in depression, also exhibit diverse expression trends across cancers." (PMID 39867577, 2024). "The results showed that the expression levels of GRB10 and TDRD9 were significantly increased in depression patients compared to the control group, while the expression levels of BCL7A, GPR18, KLRG1, and THEM4 were significantly decreased, all with statistical significance." (PMID 39867577, 2024).
diphtheria (1 paper, 2019). A Gram-positive bacterial infection caused by Corynebacterium diphtheriae. "Cellular senescence in the BM, indicated by expression of p21 in total BMMCs, as well as in highly-differentiated and/or senescent CD8+CD57+ and senescent CD8+KLRG-1+ T cells was associated with lower diphtheria-specific antibodies in the periphery." (PMID 31462901, 2019). "A negative impact on diphtheria-specific antibodies was also observed for CD8+ T cells expressing senescence associated genes such as the cell cycle regulator p21 (CDKN1A), KLRG-1, and elevated levels of reactive oxygen species (ROS)." (PMID 31462901, 2019). "Diphtheria-specific antibody concentrations negatively correlated with the mean fluorescence intensity (MFI) of p21 in all BMMCs (p = 0.0487), as well as with the percentage of CD8+CD57+and CD8+KLRG-1+ BM T cells expressing p21 (p = 0.0043 & 0.0013 respectively)." (PMID 31462901, 2019).
enteritis (1 paper, 2021). Inflammation of the small intestine. "Next, we performed flow cytometry on spleen lymphocytes from mice with DSS‐induced enteritis to identify changes in their expression of KLRG1." (PMID 33569850, 2021). "Interestingly, mice with DSS‐induced enteritis displayed a significantly higher number and proportion of KLRG1‐positive cells than the control group." (PMID 33569850, 2021). "Consistently, our results revealed that KLRG1 expression was significantly increased in the splenic lymphocytes of mice with DSS‐induced enteritis, whereas in vitro experiments confirmed that E‐cadherin could bind to KLRG1." (PMID 33569850, 2021).
experimental autoimmune encephalomyelitis (1 paper, 2016). An autoimmune demyelinating disease of the central nervous system that is produced experimentally in animals by the injection of homogenized brain or spinal cord in Freund's adjuvant. "It has been reported that KLRG1+ Treg cells elevated in a mouse model of experimental autoimmune encephalomyelitis (EAE)." (PMID 27557510, 2016).
filariasis (1 paper, 2021). "We expanded on this analysis further by simultaneously analyzing these subsets with their expression of Tim-3, LAG-3, PD-1, CD39, and KLRG-1 and building a comprehensive picture of exhausted T cells during filariasis." (PMID 34485170, 2021).
graft versus host disease (1 paper, 2022). An immune system disorder that occurs after allogeneic hematopoietic stem cell transplant and is a reaction of donor immune cells against host tissues. "Regarding graft versus host disease (GVHD), ST2+ Tregs ameliorate the intestinal damage through an IL-33 dependent increase of a KLRG1+ subpopulation." (PMID 35572605, 2022).
hip fracture (1 paper, 2014). Traumatic or pathological injury to the hip in which the continuity of either the femoral head, femoral neck, intertrochanteric or subtrochanteric regions is broken. "However, significant differences were seen in the percentage of KLRG1+ve CD8 T cells between our groups, F = 3.91, p = .02, η2 = .12, driven by an increase in hip fracture patients with depressive symptoms compared with healthy controls (p = .03)." (PMID 25628751, 2014).
invasive breast carcinoma (1 paper, 2021). A carcinoma that infiltrates the breast parenchyma. "In this work, we observed that higher expression of the signature genes CD4, KLRG-1, and B3GAT1 correlated with a higher survival rate when we analyzed the OS of patients from two invasive breast carcinoma cohorts from the TCGA consortium." (PMID 34386013, 2021).
kidney cancer (1 paper, 2019). Primary or metastatic malignant neoplasm involving the kidney. "Although KLRG-1+ CD4 T cells showed a higher frequency in tumors compared with blood from kidney cancer patients, they displayed similar frequencies in blood and tumors from patients with the remaining cancer types." (PMID 31709176, 2019).
liver cancer (1 paper, 2019). An epithelial or non-epithelial malignant neoplasm that arises from the liver. "Of note, five liver cancer patients showed a distinct shared subset of 2B4+TIGIT+KLRG-1+1PD-1–Tim-3–CTLA-4– CD8 TILs." (PMID 31709176, 2019).
metabolic syndrome (1 paper, 2015). A cluster of metabolic risk factors for CARDIOVASCULAR DISEASES and TYPE 2 DIABETES MELLITUS. "KLRG1 expression was associated with age, metabolic syndrome, visceral adipose tissue, and high muscle mass." (PMID 26611787, 2015). "Associations of KLRG1 expression and metabolic syndrome, VAT and lLMI were also observed in the individual subsets." (PMID 26611787, 2015). "VAT and metabolic syndrome were associated with higher KLRG1 expression in CD28+ and CD28− cells." (PMID 26611787, 2015). "In participants with metabolic syndrome, the proportion of KLRG1+CD28− cells increased by 14 % in unadjusted analyses, and by 18 % in adjusted analyses (Unadjusted P = 0.05, adjusted P = 0.04), compared to those without metabolic syndrome." (PMID 26611787, 2015).
myelodysplastic syndrome (1 paper, 2025). A clonal hematopoietic disorder characterized by dysplasia and ineffective hematopoiesis in one or more of the hematopoietic cell lines. "KLRG1 has been documented to be highly expressed in NK cells infiltrating various solid tumors and leukemias, including breast cancer and myelodysplastic syndromes (MDS)." (PMID 40249925, 2025).
myocarditis (1 paper, 2025). Myocarditis is a condition that is characterized by inflammation of the heart muscle (myocardium). "TCR sequencing revealed expansions of CD8 GZMK + GZMA + and CD8 PRF1 + GZMA + T cells in myocarditis patients, along with increased activation markers CD69 and KLRG1, supporting the idea that specific cytotoxic CD8 T cell groups promote inflammation." (PMID 41510228, 2025).
myositis (1 paper, 2025). "In Dataset D, mDC-specific genes from all three subsets were generally more strongly correlated with markers of the IFN-II pathway, T cell markers (including TBX21 and KLRG1), and macrophages for IBM patients than other myositis and CTRL patients." (PMID 40502583, 2025). "Furthermore, in our snRNA-seq analysis, cDC1 marker expression in myeloid cells was positively correlated with KLRG1 expression in T & NK cells from IBM samples, something that was not true when using all myositis and CTRL samples." (PMID 40502583, 2025).